METTL3 (methyltransferase 3, N6-adenosine-methyltransferase complex catalytic subunit)
Diseases named in the same sentence as METTL3 in open-access papers (continued):
Sharing a sentence is not in itself a finding about the gene and the disease.
tumor (continued). "Bioinformatic analyses revealed that through METTL3 and IGF2BP2, circQSOX1 was upregulated and sponged with miR-326 and miR-330-5p to promote PGAM1 expression, which further activated glycolysis and cytotoxic T-lymphocyte-associated antigen-4 (CTLA-4) expression, contributing to tumor immune escape." (PMID 41373022, 2025). "By examining the interplay between METTL3 levels and immune cell infiltration in different OS subtypes, we may uncover novel therapeutic strategies that not only target METTL3 but also enhance anti‐tumour immunity." (PMID 40052548, 2025). "In addition, JNK signaling facilitates tumor immune evasion through a METTL3‐dependent pathway." (PMID 39802639, 2025). "Through the downstream JAK‐STAT signaling pathway, METTL3 lactylation promotes the expression of immunosuppressive effector molecules such as interleukin (IL‐6, IL‐10, and inducible nitric oxide synthase), ultimately promoting tumor immune evasion and accelerating tumor growth and proliferation." (PMID 40443721, 2025). "Research has shown that METTL3, a methyltransferase or “writer”, acts primarily as an oncogene in several cancers including breast cancer, leukemia, glioblastoma, and more, but has also been shown to have a role as a tumor suppressor in cancers such as renal cell carcinoma and bladder cancer." (PMID 40243425, 2025). "However, STM2457 inhibits METTL3, thereby reducing tumor progression." (PMID 40823087, 2025). "However, there are few studies on METTL3 regulating tumour angiogenesis." (PMID 39820521, 2025). "Yet we still lack state-resolved, base-level maps of RNA modifications within CAF subtypes, making it unclear whether iCAFs preferentially export writers while myCAFs rely on paracrine induction of tumor METTL3—or whether specific readers (IGF2BPs vs. YTHDFs) dominate in each niche." (PMID 41280938, 2025). "In terms of disease, the abnormal expression of METTL3 is closely related to the occurrence and development of a variety of cancers, and may affect the behavior of tumors by regulating the proliferation, metastasis and drug resistance of tumor cells." (PMID 40678060, 2025). "However, the role of METTL3 in modulating the tumour microenvironment remains poorly understood." (PMID 39568154, 2024). "In addition, HPV vaccines can increase tumor sensitivity to anti-PD-1 therapy by downregulating METTL3 in tumor tissue, with the combination of HPV vaccine and PD-1 monoclonal antibodies producing enhanced immune cell infiltration compared to PD-1 blockade alone." (PMID 38030537, 2024). "However, in certain cases, contrary results have been reported for similar tumors, implying that METTL3 may at times function as a tumor suppressor." (PMID 39054967, 2024). "Interestingly, METTL3 was found to act as an oncogene or a tumor suppressor." (PMID 38966069, 2024). "Despite employing multiple models and experiments to substantiate the significant role of the METTL3/miR-151-5p/LYPD3 axis in enhancing the metastatic potential of HNSCC, it is essential to recognize that this represents only one potential mechanism underlying tumor metastasis." (PMID 39009906, 2024). "Therefore, METTL3 might play a tumor-suppressor role and it could be a potential biomarker for predicting the prognosis of patients with HR + HER2-BC." (PMID 38961497, 2024). "Additionally, we also found that the rs1263790 G allele of METTL3 had a protective effect of HBV‐HCC OS, suggesting the genetic variants of METTL3 might serve as a potential tumour biomarker in HBV‐HCC." (PMID 39163514, 2024). "Depending on the cancer type, the METTL3 may act as an oncogene or tumor suppressor." (PMID 38966069, 2024). "Therefore, we sought to explore in A549 and PC9 cells whether METTL3 levels determine the degree of sensitivity of tumor cells to ferroptosis." (PMID 38221933, 2024). "Similarly, METTL3 expression was higher in HCC tumor tissues than in adjacent normal tissues." (PMID 38693111, 2024).
tumor (continued). "Despite the normal 1:1 ratio formation between METTL3 and METTL14 in healthy cells, gene mutations, abnormal regulation, or changes in environmental factors during the tumor development process may disrupt this balance, resulting in differences in their expression and function." (PMID 38965238, 2024). "Therefore, METTL3 is expected to be a novel target for tumor-targeted therapy." (PMID 38166703, 2024). "Interestingly, the addition of atezolizumab, an anti-PD-L1 antibody, partially restored the anti-tumor effects of T cells, suggesting that the immunosuppressive role of METTL3 may be mediated through PD-L1." (PMID 39720723, 2024). "METTL3-mediated m6A methylation renders the mRNA of lipid metabolism-related genes unstable and affects downstream lipid accumulation.This instability may lead to dysregulation of lipid metabolism and facilitate tumor cell growth and immune escape." (PMID 38166703, 2024). "Various research demonstrated that polarized M2 macrophages secrete a bunch of cytokines, and chemokines to promote tumor progression 48, thereby, we hypothesized whether the METTL3-mediated m6A methylation in HCC cells was induced by cytokine secreted from M2 macrophages." (PMID 39247822, 2024). "Notably, METTL3 also decreases the stability or translation efficiency of tumour‐suppressor genes." (PMID 38545841, 2024). "In addition, we examined CYP19A1 protein expression and the intratumoural E2 concentration in lung lesions of KO-NC and KO-METTL3 tumours in the tail-vein injection model, and the results showed that CYP19A1 protein and E2 levels were significantly decreased after METTL3 knockout." (PMID 38238831, 2024). "In addition, non-coding RNAs can participate in tumor progression by regulating METTL3 expression." (PMID 38166703, 2024). "Moreover, METTL3 inhibits tumor growth by promoting cell cycle G0/G1 arrest." (PMID 39289775, 2024). "Additionally, the intensified inhibition of colony formation after cisplatin treatment may depend on METTL3 expression and tumor localization." (PMID 38966069, 2024). "Additionally, depletion of METTL3/METTL14 sensitizes tumor cells to IFN‐γ treatment." (PMID 36810108, 2023). "However, METTL3 can act either as an oncogene or a tumor suppressor in TC, depending on the specific cellular context, which suggests that approaches to both induce and suppress METTL3 could represent potential treatment options for patients with TC." (PMID 37915103, 2023). "Thus, cholesterol inhibition mitigated METTL3-induced immunosuppression and tumor growth in mice." (PMID 37586322, 2023). "In addition, METTL3 was been reported to shape the tumor microenvironment (TME)." (PMID 37907575, 2023). "Further, Mettl3 is also related to the chemosensitivity of cisplatin, and it might be possible to determine the chemotherapeutic dose of cisplatin by detecting the expression of Mettl3 in patients’ tumor tissues." (PMID 37007040, 2023). "Furthermore, METTL3 is involved in stabilizing the mRNA of HK2 and SLC2A1 (GLUT1), and degrading the mRNA of APC; all these effects are associated with the glycolysis and proliferation of tumor cells." (PMID 37965577, 2023). "However, some studies have shown that METTL3 and a highly m6A-modified state may suppress tumor development." (PMID 37964279, 2023). "However, it has been reported that fear stress may induce upregulation of METTL3 to promote tumor progression through inhibition of ferroptosis, which functions by enhancing the stability of FSP1 mRNA." (PMID 37189411, 2023). "Thus, METTL3 can acts as a tumor promoter in in chronic myelocytic leukemia cells." (PMID 36835633, 2023). "Mechanically, the level of Mettl3 in tumor cells and tumor-infiltrating immune cells potentiate the density of myeloid-derived suppressor cells (MDSCs) and attenuate the proliferation of T lymphocytes in the tumor microenvironment, as well as hinder their function." (PMID 37007040, 2023).
tumor (continued). "Previous investigations have shown that Mettl3 plays a critical role in promoting cancer development in diverse tissue types of cancer, such as affecting the development of gastrointestinal malignancies by affecting tumor proliferation, angiogenesis, apoptosis, and metastasis." (PMID 37007040, 2023). "We then assessed whether the in vitro chemotherapeutic effects of Mettl3 deletion in BMMSCs would translate into a tumor response in vivo by intravenously injecting 2 × 105 MLL-AF9 AML cells into nonirradiated Prrx1-CreERT2;Mettl3fl/fl mice and Mettl3fl/fl mice to establish a systemic AML model." (PMID 38052820, 2023). "In-depth studies on METTL3 affecting the expression of various drug resistance-related genes through m6A modification can help us better understand the mechanism of tumor drug resistance and provide new therapeutic strategies for chemotherapy-resistant tumor patients." (PMID 37996892, 2023). "However, METTL3 has also been reported as a tumor suppressor in CRC." (PMID 36348020, 2023). "Increasing evidence suggests that numerous m6A targets contribute to tumorigenesis, including Snail, CTNNB1, NANOG, APC, and genes associated with the Akt/mTOR pathway However, conflicting reports have indicated that METTL3 may function as a tumor suppressor in certain tumor types." (PMID 38012755, 2023). "In human pathophysiology, METTL3 was considered an essential factor that functioned a crucial role in multiple stages of the RNA life cycle, and its upregulation could influence m6A modifications in mRNAs of key target genes to stimulate tumor formation." (PMID 37344779, 2023). "However, sometimes METTL3 also acts as a tumor suppressor in TC." (PMID 37915103, 2023). "However, it is also reported that METTL3 serves as a tumor suppressor in TC." (PMID 37915103, 2023). "Interestingly, in a lactate-enriched TIME, lactylation drove METTL3 upregulation in tumour-infiltrating myeloid (TIM) cells and enhanced the immunosuppressive function of TIM cells through YTHDF1-mediated Jak1 translation and the subsequent phosphorylation of STAT3." (PMID 36859310, 2023). "This indicates that METTL3 could also act as a tumour suppressor in PCa." (PMID 37284313, 2023). "Furthermore, METTL3 deficiency suppresses TLR signaling-mediated macrophage activation by reducing degradation of IRAKM, which increases susceptibility to bacterial infection and enhancing tumor growth in mice." (PMID 37928272, 2023). "We next clarified whether METTL3 affected the CAFs' effect on tumor growth in vivo." (PMID 37056933, 2023). "TIMs play an important role in tumour immune escape, and lactylation enriched in the promoter of methyltransferase‐like 3 (METTL3) region drives the high expression of METTL3, which, in turn, strengthens the immunosuppressive capacity of TIMs through the METTL3/m6A/JAK1/STAT3 axis." (PMID 37060186, 2023). "Interestingly, sometimes METTL3 also acts as a tumor suppressor." (PMID 36830614, 2023). "Therefore, METTL3-mediated recruitment or expression of key enzymes in DNA damage repair may facilitate tumor progression and chemoresistance in HCC." (PMID 35223847, 2022). "Therefore, the role of METTL3 in the tumor immune microenvironment warrants further investigation." (PMID 36614956, 2022). "However, METTL3 was found to be a tumor suppressor in triple-negative breast cancer (TNBC)." (PMID 35462896, 2022). "Moreover, the protein level of METTL3 was significantly correlated with age and tumor size." (PMID 36058919, 2022). "METTL3 may play essential roles in modulating tumor immune responses and EMT pathways." (PMID 36614956, 2022). "In addition, METTL3 deficiency impairs YTHDF1-mediated SPRED2 translation, which enhances NF-κB and STAT3 activation via the ERK pathway, resulting in increased TAM-induced Treg infiltration into TME and tumor metastasis." (PMID 35794625, 2022).
tumor (continued). "Additionally, in the subcutaneous xenograft models, tumoral METTL3 inhibition and anti-PD-L1 therapy could both markedly limit tumor growth of the mice as compared to the control groups." (PMID 35197058, 2022). "Thus, METTL3 may participate in regulation of the tumor immune microenvironment and may serve as a potential prognostic biomarker of the effects of immune therapies." (PMID 36614956, 2022). "In addition, several studies confirmed that METTL3 knocked-down (METTL3-KD) represses the proliferation, tumorigenic invasion, and migration capacity of PCa cells in a catalytic-dependent manner in vitro, and reduces tumour growth in vivo." (PMID 35205419, 2022). "Besides, high METTL3 expression in cancerous tissues was significant correlated with advanced T stage and poor tumor differentiation among HNSCC patients, and HNSCC patients with high expression of METTL3 had worse overall survival using our tissue microarray (TMA) (n = 100, p = 0.001)." (PMID 35287752, 2022). "Therefore, METTL3 was involved in tumor immune response in HPV related cancer." (PMID 35813476, 2022). "These inconsistent studies suggest that METTL3 may play opposite roles in different tumor cells." (PMID 36003776, 2022). "Notably, knockdown of AKR1B10 rescued the tumor-promoting effects induced by METTL3 overexpression." (PMID 36476503, 2022). "Indeed, in tumor-infiltrating myeloid cells – a key population involved in tumor immune escape – environmental lactate was shown to increase the transcriptional expression of oncogene methyltransferase like 3 (METTL3) through lactylation of histone H3K18." (PMID 36226054, 2022). "Additionally, our comprehensive pan-cancer analysis suggested that METTL3 is involved in regulating the tumor immune microenvironments and epithelial–mesenchymal transition via modulating RNA modification and metabolism, making it a potential therapeutic target." (PMID 36614956, 2022). "Additionally, METTL3 could promote tumor growth by regulating m6A modification to facilitate EMT progression in various types of cancers." (PMID 34666602, 2021). "The results of KEGG analysis show that genes regulated by METTL3 are also widely involved in cellular responses to toxic substances, oxidative stress and antigen presentation pathways, which may affect the tumor cell response to chemotherapy, anti-vascular therapy and immune checkpoint inhibitors." (PMID 34814861, 2021). "Likewise, overexpression of Mettl3 in K14+ CSCs cells accelerated tumor growth and progression." (PMID 33681207, 2021). "Thus, METTL3 in Tregs may suppress the anti-tumor immune response by maintaining the immunosuppressive function of Tregs." (PMID 34526985, 2021). "Moreover, METTL3 inhibition could increase the NFIC transcriptional level to repress tumor growth and lung metastasis in vivo." (PMID 34666602, 2021). "METTL3 may acts as oncogene or as tumor suppressor, depending on the cellular context." (PMID 35474700, 2021). "Moreover, METTL3-deficiency in macrophages impairs the YTHDF1-mediated translation of SPRED2, which enhances the activation of NF-kB and STAT3 through the ERK pathway, leading to increased tumor growth and metastasis." (PMID 34526985, 2021). "Similarly, another study reported that CRC patients with elevated expression of METTL3 showed significantly better survival than those with lower METTL3 expression; up-regulation of METTL3 significantly reduced tumor proliferation, migration and invasion of CRC cells." (PMID 33795529, 2021). "However, it is unclear which circRNAs may regulated the level of METTL3 in the tumorigenesis and tumor progression of TNBC." (PMID 35004298, 2021). "On the other hand, METTL3 may also function as a tumor suppressor in several cancers." (PMID 33879256, 2021). "Additionally, the functional activation of METTL3 could promote rapid tumor growth and EMT, which dependent of the activation of PI3K/AKT pathways and the overexpression of EZH2." (PMID 33879256, 2021).
tumor (continued). "METTL3 was reported to play either oncogenic or/and tumor-suppressive functions by different groups, which may be explained by tumor heterogeneity and/or different model systems used for the study, and further comprehensive and detailed studies are warranted to gain a better view." (PMID 34531875, 2021). "We next asked whether myeloid-specific deletion of Mettl3 affects tumour growth." (PMID 33654093, 2021). "To validate whether FBXW7 contributes to the anti-tumor phenotype regulated by METTL3, we generated stable cells expressing the indicated genes to determine whether FBXW7 overexpression could rescue the effects of METTL3 knockdown on the biological behavior of HCC827 or PC9 cells." (PMID 33676554, 2021). "We next asked whether Mettl3 in myeloid cells regulates tumour progression." (PMID 33654093, 2021). "Through analysis, we found that the expression of METTL3 is only related to the overall survival time of patients, and has nothing to do with the pathological stage, which suggests that METTL3 may affect the patient’s response to anti-tumor therapy and thus affect the prognosis." (PMID 34814861, 2021). "Furthermore, to determine whether METTL3 can affect tumour metastasis, B16 or LLC cells were injected into mice via the tail vein." (PMID 33654093, 2021). "Additionally, METTL3 might affect tumor metastasis through promoting the maturation of pri-miR-1246." (PMID 33015074, 2020). "Moreover, the colony‐forming capacity of tumour cells was improved in METTL3‐up‐regulated cells." (PMID 33090698, 2020). "Importantly, we found that CD33 and METTL3 co-localized in some tumour-infiltrated immune cells." (PMID 33059689, 2020). "In contrast, some studies have shown that METTL3 might be a tumour suppressor." (PMID 32615646, 2020). "Importantly, the function of METTL3 was found to be changed in several tumor cells." (PMID 32033081, 2020). "Moreover, METTL3 expression in the primary tumor was elevated with increased M stage and TNM stage." (PMID 32175271, 2020). "Notably, depletion of METTL3 by using in vivo‐optimized RNAi significantly rescued the xenograft tumor growth compared with the control under sorafenib treatment, which showed increased proliferation, autophagy, and angiogenesis as indicated by Ki67, LC3‐B, and VEGF‐A, respectively." (PMID 32368828, 2020). "In addition, overexpression of miR‐186 inhibits HB cell proliferation, migration and invasion in vitro, and inhibits HB tumour development and lung metastasis in vivo, which could be partially reversed by the overexpression of METTL3." (PMID 31967701, 2020). "Furthermore, silencing METTL3 led to an inhibition in DLBCL cell proliferation both in vitro and in vivo, suggesting that METTL3 may act as a pro-tumor gene involved in the pathogenesis of DLBCL." (PMID 33061938, 2020). "Overall, these data support the notion that METTL3-catalyzed m6A methylation can affect the activities of certain tumor-specific mRNAs, eliciting a change in the expression of the oncoproteins and biological behaviors of the tumor cells and facilitating the cancer development." (PMID 33061938, 2020). "Interestingly, only one study indicated that METTL3 is a tumor suppressor that inhibits CRC cell proliferation, migration, and invasion, which may be attributed to differences in tumor tissue origin, intratumoral heterogeneity, and research methods." (PMID 32429972, 2020). "Here, our data suggest that METTL3-mediated m6A RNA modification is positively associated with the increase in MDSC expansion and affects tumour development and prognosis in CC and induces CD33 + cells to differentiate into MDSCs in the tumour microenvironment." (PMID 33059689, 2020). "Interestingly, the role of METTL3 in cancer seems to be dependent on tumor types." (PMID 32068977, 2020). "Moreover, inhibition of METTL3 with siRNA treatment could significantly reduce the tumor size in PDX models." (PMID 31230592, 2019).